ZNF274 (zinc finger protein 274)
Description:
Probable transcription repressor. Specifically binds to the 3'-end of zinc-finger coding genes and recruiting chromatin-modifying proteins such as SETDB1 and TRIM28/KAP1, leading to transcription repression. The SETDB1-TRIM28-ZNF274 complex may play a role in recruiting ATRX to the 3'-exons of zinc-finger coding genes with atypical chromatin signatures to establish or maintain/protect H3K9me3 at these transcriptionally active regions.
Synonyms: Zf2; ZKSCAN19; ZSCAN51; HFB101
Tractability: PROTAC: ubiquitination databases record sites on it.
Gene: Protein-coding gene on chromosome 19 (58,183,029 to 58,213,573, forward strand). Ensembl gene ENSG00000171606.
Subcellular location: Cytoplasm; Nucleus, nucleolus
Subcellular location (Human Protein Atlas): Nucleoplasm; Centrosome
Pathways (Reactome):
Gene expression (Transcription): Generic Transcription Pathway
Gene Ontology:
Molecular function: chromatin binding; protein binding; sequence-specific DNA binding; sequence-specific double-stranded DNA binding; DNA-binding transcription factor activity, RNA polymerase II-specific; RNA polymerase II cis-regulatory region sequence-specific DNA binding
Biological process: chromatin remodeling; negative regulation of transcription by RNA polymerase II; regulation of DNA-templated transcription; regulation of transcription by RNA polymerase II
Cellular component: nucleolus; nucleus; cytoplasm
Genetic constraint (gnomAD): Loss-of-function variants: 29 observed, 43.93 expected, observed/expected ratio (o/e) 0.66, 90% interval 0.49 to 0.9. The upper end of that interval is the gene's LOEUF score, 0.9, which puts it in group 3 of 6, group 1 being the genes least tolerant of losing a copy. Missense variants: 679 observed, 815.37 expected, observed/expected ratio (o/e) 0.83, 90% interval 0.78 to 0.89. Synonymous variants: 292 observed, 306.71 expected, observed/expected ratio (o/e) 0.95, 90% interval 0.86 to 1.05.
Homologues: Orthologues: macaque ZNF274 (96% identical), chimpanzee ZNF274 (95% identical), dog ZNF274 (72% identical), rabbit ZNF274 (71% identical), pig ZNF274 (59% identical), mouse Zfp110 (58% identical), rat Zfp110 (58% identical), mouse Zfp369 (57% identical), Drosophila melanogaster CG12391 (12% identical), Drosophila melanogaster hb (11% identical), zebrafish plagl2 (9% identical), zebrafish ovol1a (8% identical), and 5 more. Paralogues in human: ZKSCAN2 (24% identical), ZSCAN32 (24% identical), ZNF18 (23% identical), ZSCAN29 (23% identical), ZNF202 (22% identical), ZNF496 (20% identical), ZNF174 (17% identical), ZSCAN5A (17% identical), ZNF446 (17% identical), ZSCAN5C (17% identical), ZSCAN1 (17% identical), ZSCAN5B (17% identical), and 17 more.
Diseases named in the same sentence as ZNF274 in open-access papers:
ZNF274 is named in the same sentence as 9 diseases in open-access papers, as found by Europe PMC text mining. Sharing a sentence is not in itself a finding about the gene and the disease. The quoted sentences say what the papers report.
Prader-Willi syndrome (2 papers, 2023 to 2024). "ZNF274 encodes a Kruppel-associated box zinc finger protein that contains 5 C2H2 zinc finger domains and is a transcriptional repressor involved in a wide range of processes, including repression of the Prader-Willy syndrome maternal gene expression in neurons." (PMID 36400229, 2023).
intellectual impairments (1 paper, 2024). "Connections with PWS and schizophrenia pathogenesis suggest that severe intellectual impairments may arise from the dysregulation of ZNF274 expression." (PMID 39270011, 2024).
liver disease (1 paper, 2017). "When the analysis was replicated in 39 independent liver samples from NAFLD obese patients, high transcription levels in CpG regions of zinc finger protein 274 (ZNF274), PGC1A, and sterol regulatory element binding transcription factor 2 (SREBP2) were associated with liver disease." (PMID 28250848, 2017).
schizophrenia (1 paper, 2024). A major psychotic disorder characterized by abnormalities in the perception or expression of reality. "Besides, we identified a potential association between ZNF274, the regulation of PCDH, and schizophrenia pathogenesis." (PMID 39270011, 2024).
ZNF274 also shares sentences with these, for which no sentence is quoted: tumor (2 papers); cancer (1); congenital cataracts (1); neuropathy (1); oligodendroglioma (1).